TERT (telomerase reverse transcriptase)
Diseases named in the same sentence as TERT in open-access papers (continued):
Sharing a sentence is not in itself a finding about the gene and the disease.
tumor (continued). "Mutations in the promoter region of the TERT gene have emerged as key molecular alterations in gliomas, influencing tumor progression, prognosis, and treatment response." (PMID 40628732, 2025). "In contrast, TERT (telomerase reverse transcriptase) promoter mutations in conjunction with a RAS mutation are strongly associated with tumor aggressiveness, recurrence, and poor prognosis." (PMID 40940948, 2025). "The aim of this study was to evaluate the diagnostic potential of a urinary tumor DNA detection panel, which included eight common point mutations in TERT, GPR126, FGFR3, and PIK3CA genes, in UBC." (PMID 41515564, 2025). "Of note, TERT amplification increased the likelihood of tumor recurrence (RR = 3.656, P = 0.010) and the risk of death of disease (RR = 7.930, P = 0.0004)." (PMID 40272676, 2025). "Our predictive model highlights the association of elevated AXL expression, TERT promoter mutation, and an aggressive tumour subtype with the risk of RAI refractoriness." (PMID 40241101, 2025). "Molecular biomarkers, including Ki-67 proliferation index, NF2 gene status, TERT promoter mutations, and H3K27me3, which are pivotal for tumor classification and prognosis have been the subject of study of recent radiomic studies." (PMID 41339597, 2025). "First, the patient’s tumor tested positive for a telomerase reverse transcriptase (TERT) mutation, specifically the C228T variant." (PMID 39974235, 2025). "All six patients who developed distant metastases had tumours harbouring additional TERT-p mutations." (PMID 40107205, 2025). "Since 2013, C228T and C250T TERT promoter mutations have been found in many other tumor types originating from organs with a stable population of cells that do not undergo constant turnover and where telomerase is not normally expressed." (PMID 41175860, 2025). "For the recurrent tumor in this episode, molecular testing revealed the presence of a TERT promoter C250T mutation, a finding confirmed by Sanger sequencing." (PMID 41013491, 2025). "Telomere dysfunction has been implicated in malignant transformation of benign GCT to malignancy: malignant H3.3-mutated tumours are enriched for a variety of alterations in Telomerase Reverse Transcriptase (TERT)." (PMID 37828086, 2025). "One tumor (case #8) exhibited a TERT promoter mutation (C228T), which was detected through NGS analysis." (PMID 40227557, 2025). "Several tumors, including OSCC have shown an increase in TERT activity through promotor mutation as well as expression in tumour cells." (PMID 40307280, 2025). "There were 4 patients with NGS on tumor tissue, with 3 patients noted to have a TERT promoter mutation." (PMID 40828887, 2025). "Two mutually exclusive mutations close to the transcription start site, which create de novo ETS binding sites and putatively lead to aberrant binding of specific ETS factors, are believed to underlie the tumour‐promoting upregulation of TERT activity." (PMID 40214124, 2025). "Further, OSCC with TERT promotor mutation also have an increased risk of local regional spread, which can be correlated with increased tumor size due to increased proliferation of tumor cells." (PMID 40307280, 2025). "The TERTp mutation increases tumor cell fitness by upregulating TERT expression and telomerase activity." (PMID 41354838, 2025). "This is likely due to the contribution of tumor suppressors and oncogenes to cancer aneuploidies, such as the TERT oncogene, encoded on chromosome 5p, and tumor suppressors like MAP3K1, encoded on chromosome 5q." (PMID 39930267, 2025). "Amplifications in the ALK, DYNC1I1, and TRRAP genes were found in one tumor, which also showed a point mutation in TERT (each 5%)." (PMID 40227833, 2025).
tumor (continued). "Mutations in the TERT promoter have been shown to upregulate telomerase expression, resulting in aggressive tumor characteristics." (PMID 40711866, 2025). "TERT is also associated with various telomere-length-independent functions that contribute to tumor development, including the enhancement of proliferation, resistance to apoptosis, and the promotion of inflammation, invasion, and metastasis." (PMID 40227701, 2025). "Among the most clinically relevant mutations, BRAF V600E and TERT promoter mutations are strongly associated with malignancy and aggressive tumor behavior." (PMID 40940948, 2025). "Patients with tumor TERT mutations in our research had a worse prognosis than those without mutations (mean OS: 10.1 vs. 15.9 months, respectively), corresponding to a 43% reduction in OS time." (PMID 39739534, 2025). "Compound 17, which exhibited cytotoxicity against PANC−1 cells, was linked to 55 targets, including key targets such as EGFR, AKT1, CDK1, CDK2, MMP9, PIK3CG, and TERT, closely associated with tumour cell proliferation, migration, and apoptosis." (PMID 41006588, 2025). "Dual driver mutations, especially when the partner includes TERT mutation, have been associated with more aggressive tumor behavior." (PMID 40226091, 2025). "TERT promoter mutations are associated with tumor progression, invasive behavior, and poor clinical outcomes." (PMID 40805132, 2025). "TERT promoter mutations increase telomerase activity, allowing for indefinite tumor cell replication, while EGFR amplifications lead to continuous activation of intracellular signaling pathways that promote cell proliferation." (PMID 41567539, 2025). "Frequent EGFR amplifications and TERT gene promoter mutations lead to the deregulation of tumor cell proliferation and increased aggressiveness." (PMID 41465586, 2025). "Aberrant TERT expression enables cancer cells to acquire replicative immortality, a hallmark of tumor progression." (PMID 41155227, 2025). "Key biomarkers such as MGMT promoter methylation, IDH1/2 mutations, EGFR amplification, and TERT promoter mutations, etc., are examined for their roles in prognosis, therapeutic response, and tumor classification." (PMID 39767571, 2024). "Relapse-free survival is shortened in TERT mutated cases versus wild type (16.13 ± 6.15 months vs. 101.34 ± 9.09 months), as well as overall survival and tumor specific survival." (PMID 39458070, 2024). "A large number of genetic association studies have demonstrated that TERT promoter mutation is associated with multiple characteristics of aggressive tumor behaviors and patients with TERT promoter mutation had a higher risk of recurrence and mortality." (PMID 38313800, 2024).
tumor (continued). "Here we experimentally assessed the RNA sequencing expression patterns associated with TERT transcription in 1039 human cancer samples of 27 tumor types." (PMID 38859942, 2024). "We found that TERT promoter mutations frequently overlapped tumor aDMRs but, interestingly, tended to be found on the less methylated allele (Wilcoxon rank-sum test, p = 0.13 for average allele-specific methylation in 12 mutated cases)." (PMID 39406235, 2024). "Numerous studies have demonstrated a robust oncogenic function of the genetic duets of BRAF/RAS mutations and TERT promoter mutations in driving tumor aggressiveness and poor clinical outcomes of PTC." (PMID 38735658, 2024). "The hotspot TERT promoter mutation (C228T), was further confirmed by ddPCR in both patient’s tumor biopsy and in the HCB-541 cell line." (PMID 38565739, 2024). "Mutations in the TERT promoter region result in upregulation of gene expression, thereby inducing the activation of telomerase activity and conferring tumor cells with unlimited proliferative potential." (PMID 38798094, 2024). "On univariate analysis, age ≥45 years (p < 0.0001), tumor size (p = 0.0052), distant metastasis (p < 0.0001) and TERT mutation (p < 0.0001) were significantly related to DTC-specific survival." (PMID 38812819, 2024). "Then we stratified all the PTC samples into two groups according to the tumor stage, and found that TERT hypermethylation was associated poor clinical outcomes in advanced PTC patients (stage III/IV)." (PMID 38313800, 2024). "In the present study, the TERT promoter mutation in oSFT manifested in a case with an unfavorable prognosis, comprising aggressive local tumor growth, local recurrence, and eye loss." (PMID 38392213, 2024). "It has been observed that there is a link between TERT mutations and tumour aggressiveness as well as distant or local metastasis." (PMID 39558949, 2024). "This tumour also harboured additional genetic abnormalities, including TERT promoter (C228T) mutation, PTEN mutation, and homozygous CDKN2A/2B deletion." (PMID 39014476, 2024). "Compared to the initial resected tumor specimen, the recurrent tumor possessed a loss of heterozygosity of the 1p, 10q, 17q and 19q chromosomes, as well as a new C228T TERT promoter mutation, while the status of wild-type IDH1/IDH2 was unchanged." (PMID 39590169, 2024). "Previous studies have reported some prognostic factors such as distant metastasis, age, tumor size, vascular invasion, TERT promoter mutation, and histological subtype." (PMID 39419099, 2024). "The prevalence of TERT promoter mutations in oSFT was 11% and occurred in a case with locally aggressive tumor growth and multiple uncontrollable, local recurrences." (PMID 38392213, 2024). "team found it will inhibit the tumour growth in brain and liver through editing the mutated TERT promoter, implying the importance and possibility of precision therapy aiming at TERT promoter mutation in HCC." (PMID 38769666, 2024). "It is notable that somatic TERT promoter mutations that activate TERT transcription show strong positive selection during tumour progression, as the prevalence of these mutations increases substantially from pre-invasive to invasive stages." (PMID 39020172, 2024). "Research has shown that mutations in the TERT gene are related to increased tumor size, invasiveness, lymph node metastasis and resistance to radiotherapy." (PMID 38607456, 2024). "Other markers, such as EGFR amplification and TERT promoter mutations, are linked to more aggressive tumor behavior and shorter survival times." (PMID 39767571, 2024). "The maximum increase was 1.6-fold for the mononucleosome cell-free DNA (cfDNA) fragments (120–280 bp), 1.9-fold for patient-specific tumor variant ctDNA level, and 5.6-fold for the TERT mutation ctDNA level." (PMID 38672658, 2024). "Mutations in the promoter region of the TERT gene can result in increased TERT expression and telomerase activity, contributing to cellular immortality and tumor growth." (PMID 38247727, 2024).
tumor (continued). "This reactivation is achieved through several mechanisms, the most common being TERT promoter mutation, observed both in tumor cells and hepatocytes within cirrhotic parenchyma." (PMID 38927059, 2024). "There are also TERT (Telomerase Reverse Transcriptase) gene mutations that occur at a later stage of tumor development and additionally contribute to tumor aggressiveness." (PMID 38540091, 2024). "TERT mutations typically provide a molecular basis for sustained tumor growth by lengthening telomere length in tumor cells, promoting unchecked proliferation, and avoiding apoptosis." (PMID 39457636, 2024). "Forty-five percent of patients had TERT promoter mutations at -124 C > T, which were substantially linked to shorter metastasis-free life, disease-specific survival, and higher tumor grade." (PMID 39239547, 2024). "Conclusively, the study found that TERT promoter mutation is significantly linked to high-risk properties (e.g., older age, larger tumor size, higher mitotic rate)." (PMID 38392213, 2024). "Batsios and colleagues studied the association between TERT and metabolism in patient-derived preclinical tumor models." (PMID 38672647, 2024). "Previous reports have demonstrated that specific radiomic features, including tumor shape, texture, and enhancement patterns, can provide valuable insights for predicting TERT promoter mutations and survival outcomes." (PMID 38798094, 2024). "Knowing the temporal occurrence of genetic and epigenetic changes in TERT locus during cancer growth is very important for the development of diagnostic and prognostic markers in diverse tumour types." (PMID 38033865, 2023). "Assessment of the mutated TERT promoter in fluid matrices of human body has already demonstrated its value for the monitoring of tumour diagnosis and recurrence." (PMID 38033865, 2023). "One study showed that most high-risk NB tumours have TERT rearrangements, MYCN amplification or ATRX mutations, all of which extend telomere length, suggesting an important role for TMM in clinical prognosis." (PMID 37958407, 2023). "TERT promoter mutation can cause telomerase overexpression in tumor tissues or cells, which can promote carcinogenesis." (PMID 37250582, 2023). "Our data demonstrates that TERT amplification status is a significant risk factor associated with reduced overall survival in a specific patient subgroup presenting with a pT1N0-3 tumor stage." (PMID 37848472, 2023). "The results revealed six independent factors, of which male sex, increased tumor size, extraglandular infiltration, TERT promoter mutations and NRAS mutation increased the risk of CLNM, while HT was a protective factor (P<0.05)." (PMID 36817603, 2023). "Activating mutations in the TERT gene increase telomerase expression, allowing some neoplasms to overcome the end-replication problem and avoid senescence." (PMID 37892022, 2023). "Overall, the c.1-124C>T hotspot mutation in the TERT promoter was found in 60% (9/15) of primary tumor specimens and 55% (6/11) of metastatic sites." (PMID 38098507, 2023). "In this subset of patients, they found that the TERT promoter mutation was found in both the lower and higher-grade tumour, and in both NF2-mutated and NF2-wildtype tumours." (PMID 36882706, 2023). "Our results revealed that high TMB, EGFR mutation, and TERT mutation had a significant association with tumour recurrence in NMIBC." (PMID 37892022, 2023). "TERT promoter sequencing showed activating mutations (C228T and/or C250T) in 73.3% of the 30 tumor samples analyzed." (PMID 36901733, 2023). "TERT promoter mutations were detected in 12 (50%) of patients via CSF, while were identified in 16 (66.7%) of patients though tumor tissue." (PMID 37822669, 2023). "First, tumor areas were identified using convolutional neural networks (CNNs), and then TERT promoter mutations within tumor areas were predicted using the CNN–recurrent neural network (CRNN) model." (PMID 36984536, 2023).
tumor (continued). "To visualize the model, we plotted a nomogram based on six independent factors (sex, HT, tumor size, extrathyroidal extension, TERT promoter mutations and NRAS mutation) in the training cohort." (PMID 36817603, 2023). "When activating hot-spot mutations in the promoter region of TERT (pTERT) occur, these result in an upregulation of telomerase complex activity and thus constitute a relevant mechanism for the immortalization of tumor cells." (PMID 38201248, 2023). "The importance of TERT mutations as a prognostic factor is exemplified by its inclusion as a signifier of grade 3 tumours in the updated WHO classification system." (PMID 37860270, 2023). "The TERT promotor mutations are now acknowledged as the most common non‐coding mutations in tumours." (PMID 37041671, 2023). "For instance, patients diagnosed with TERT promotor mutations in thyroid carcinomas showed not only higher tumor stages or more frequent distant metastases, but also experienced significantly worse survival." (PMID 37848472, 2023). "The results revealed that the EGFR mutation and the TERT mutation had a significant association with tumour recurrence." (PMID 37892022, 2023). "Point mutations in the core promoter region of the telomerase reverse transcriptase (TERT) gene have been found to occur at high frequencies in several tumour types and considered a primary cause of telomerase reactivation in cancer cells." (PMID 38033865, 2023). "Generally, the TERT activity is increased in these cancers because shorter telomeres limit the replicative potential of tumour cells and can cause genotoxic stress." (PMID 37317665, 2023). "GBM with TERT gene mutations typically exhibit more invasive and malignant biological behavior, higher tumor recurrence rate, and poorer survival rate." (PMID 37830090, 2023). "Univariate analyses revealed a significant association of TMB, EGFR mutation, and TERT mutation with tumour recurrence within 1 year (p = 0.030, p = 0.033, and p = 0.039, respectively)." (PMID 37892022, 2023). "More recent studies suggest synergistic effects with additional mutations, such as TERT promoter (TERTp) mutation, resulting in increased tumour invasion and a poor prognosis." (PMID 37374164, 2023). "All five patients were IDH1 wildtype, and four patients (except for G05) were positive for TERT mutations based on analysis of resected tumor tissue." (PMID 37717084, 2023). "A striking correlation of TERT expression in our study was a higher estimate of tumor-infiltrating CD4+ T cells, which were previously associated with improved clinical outcome of ICI therapy." (PMID 37418389, 2023). "In HCC, the TERT promoter frequently undergoes somatic mutation, consequently leading to an up-regulation in TERT expression in tumor tissues." (PMID 38163482, 2023). "The TERT promoter C228T mutation was found in 33% of primary tumours and in 36% of lymph node metastatic samples." (PMID 37352166, 2023). "Sonobiopsy enriched the plasma level of mononucleosome cfDNA fragment (120–280 bp), patient-specific tumor variant ctDNA, and TERT mutation ctDNA." (PMID 37717084, 2023).